ZMYM5 (zinc finger MYM-type containing 5)
Description:
Functions as a transcriptional regulator.
Synonyms: ZNF198L1; ZNF237; HSPC050; MYM
Tractability: PROTAC: UniProt records ubiquitination sites on it; ubiquitination databases record sites on it.
Gene: Protein-coding gene on chromosome 13 (19,823,482 to 19,864,915, reverse strand). Ensembl gene ENSG00000132950.
Subcellular location: Nucleus
Subcellular location (Human Protein Atlas): Nucleoplasm; Golgi apparatus
Gene Ontology:
Molecular function: protein binding; zinc ion binding
Biological process: negative regulation of transcription by RNA polymerase II
Cellular component: nucleus
Genetic constraint (gnomAD): Loss-of-function variants: 41 observed, 61.98 expected, observed/expected ratio (o/e) 0.66, 90% interval 0.51 to 0.86. The upper end of that interval is the gene's LOEUF score, 0.86, which puts it in group 3 of 6, group 1 being the genes least tolerant of losing a copy. Missense variants: 697 observed, 767.45 expected, observed/expected ratio (o/e) 0.91, 90% interval 0.85 to 0.97. Synonymous variants: 250 observed, 267.6 expected, observed/expected ratio (o/e) 0.93, 90% interval 0.84 to 1.04.
Homologues: Orthologues: chimpanzee ZMYM5 (99% identical), dog ZMYM5 (80% identical), rabbit ZMYM5 (77% identical), pig ZMYM5 (74% identical), mouse Zmym5 (64% identical), rat Zmym5 (63% identical), macaque ZMYM5 (51% identical). Paralogues in human: ZMYM2 (56% identical), ZMYM3 (25% identical), ZMYM4 (24% identical), ZMYM6 (17% identical), ZMYM1 (17% identical), QRICH1 (7% identical), GTF2IRD1 (6% identical), SCAND3 (6% identical), GTF2IRD2B (5% identical), GTF2IRD2 (5% identical), KIAA1958 (5% identical), GTF2I (5% identical), and 6 more.
Diseases named in the same sentence as ZMYM5 in open-access papers:
ZMYM5 is named in the same sentence as 3 diseases in open-access papers, as found by Europe PMC text mining. Sharing a sentence is not in itself a finding about the gene and the disease. The quoted sentences say what the papers report.
COVID-19 (2 papers, 2021 to 2023). A disease caused by infection with severe acute respiratory syndrome coronavirus 2. "Conversely, in COVID-19 patients who respond to treatment (f), the relative expression of ZMYM5, COL5A3, and CAMSAP1 was significantly decreased and the relative expression of DICER1 was significantly increased during hospitalization." (PMID 34256840, 2021). "Serum levels of hsa-miR-29a-3p, hsa-miR-31-3p and hsa-miR-126-3p are reduced with increased severity of COVID-19, and the relative expression levels of COL5A3, ZMYM5 and CAMSAP1 are also increased with increased severity of COVID-19." (PMID 37661862, 2023). "In COVID-19 patients who did not respond to treatment (e), the relative expression of ZMYM5, COL5A3, and CAMSAP1 was significantly increased and the relative expression of DICER1 was significantly decreased during hospitalization." (PMID 34256840, 2021).
ZMYM5 also shares sentences with these, for which no sentence is quoted: mental retardation (1 paper); ptosis (1).